TNF (tumor necrosis factor)
Diseases named in the same sentence as TNF in open-access papers (continued):
Sharing a sentence is not in itself a finding about the gene and the disease.
tumor (continued). "These molecules affect the activity of many genes, including NF-κB, which is involved in proliferation and tumor development, and is also an inflammation initiator and TNF-α downstream target." (PMID 37233761, 2023). "To confirm the reliability of the hub genes, we verified the high expression of TNF in tumor Tregs and found that the high expression of TNF was significantly related to the prognosis of gastric cancer patients." (PMID 37534250, 2023). "In vitro experiments, we investigated the expression levels of ARL4C in four tumor cell lines treated with various cytokines, namely IFNβ, IFNγ, TGFβ, and TNFα." (PMID 38178862, 2023). "Addition of Takinib significantly enhanced tumor killing in a dose-dependent manner compared to control condition rendering tumor cells more sensitive to TNFα-induced cell death." (PMID 37732732, 2023). "This destruction releases tumor antigens and increases concentrations of IL-6, TNF-α, and IFN-γ, stimulating dendritic cell maturation, NK cell activation, and T cell response promotion." (PMID 37514190, 2023). "To date, a variety of myokines has been identified, including main driver mediators of an anti-tumoral tumor microenvironment such as the interleukins (IL) IL-7, IL-15, tumor necrosis factor (TNF) and interferon-gamma (INF-γ)." (PMID 37760634, 2023). "These indirect, RANKL-mediated mechanisms act in parallel with the direct stimulation of osteoclast formation by tumor necrosis factor (TNF) α secreted from tumor cells." (PMID 36835198, 2023). "A positive feedback loop ensues whereby these cytokines, such as IL-6, IL-8, and TNF-α, amplify the inflammatory infiltrate in the tumor microenvironment and systemically." (PMID 37964946, 2023). "To examine TNF-α spatial distribution within the tumor, we performed fluorescence in situ hybridization using RNAscope probes against Tnfa, along with immunofluorescence staining of IBA1 and Elane." (PMID 37012245, 2023). "Consistently, the NF-κB target genes such as IL-6 and TNF were highly increased in both non-tumor and tumor areas of the ITF2ΔIE mice in contrast with the littermates." (PMID 37185280, 2023). "We collected TNF+ Tregs and TNF- Tregs sorted from tumor tissues and GM tissues by flow cytometry sorting." (PMID 37534250, 2023). "Together, these data suggest that TNFα produced by HSPCs in presence of tumor can act on ABS niche cells to increase the capacity of the splenic niche to support hematopoiesis." (PMID 37134077, 2023). "They discovered that neutrophils were almost exclusively found at the tumor’s periphery during the initial stages of tumor development, and TANs were more cytotoxic toward tumor cells and generated higher levels of TNF-α, NO, and hydrogen peroxide (H2O2)." (PMID 37298230, 2023). "Among them, Nelarabine was highly correlated with TNF, which has guiding clinical significance for the selection of anti-tumor therapy." (PMID 37033970, 2023). "We confirmed the results of recombinant HDGF and TNFα using 3-D organoids, but it took about 2–3 months by xenotransplantation assays, and the tumor size was always very small." (PMID 37047540, 2023). "The researchers showed that high levels of TNF-α are tumor curative, while low levels can be a source of carcinogenesis." (PMID 37280571, 2023). "Rather, EMT was associated with epigenetic and transcriptional silencing of interferon regulatory factor 6 (Irf6), which renders tumor cells less sensitive to the pro-apoptotic effects of TNF-α." (PMID 37398248, 2023). "Upregulation of CD276 promoted the immune escape of tumor cells and reduced secretion of interleukin-2 (IL-2), tumor necrosis factor-alpha (TNF-α) and other cytokines." (PMID 36713082, 2023). "illustrated that deletion of TNF receptor-associated factor 2 (TRAF2) redirected TNF signaling pathway to promote RIPK1-dependent apoptosis, thereby lowering TNF cytotoxicity threshold in tumor cells." (PMID 37876793, 2023).
tumor (continued). "TNF-α is also involved in attracting and stimulating neutrophils and monocytes to activation sites for anti-tumour immune responses." (PMID 37629081, 2023). "In contrast, the levels of IP10 were significantly increased after prolonged TNF-α treatment, which inhibited tumor cell proliferation." (PMID 36814921, 2023). "We also found a significant positive correlation between a high amount of F. nucleatum and high levels of IL-6, and TNF-α expression in the tumor tissues." (PMID 38075864, 2023). "TNF has been widely explored in preclinical and clinical cancer research because of its anti-tumor effect via immune response regulation." (PMID 36045273, 2023). "Inflammatory factors (such as interleukin‐6 and tumor necrosis factor) in the tumor microenvironment can inhibit albumin synthesis in the liver." (PMID 37434479, 2023). "In conclusion, anti-TNFα mAb demonstrated the potential to suppress tumor growth, stromal reaction, and angiogenesis, mediate a reduction in the number of TAMs, increase immunity against tumor and apoptosis, and suppress CRC progression in the TME." (PMID 36996146, 2023). "Conversely, mast cells possess the capacity to combat tumors directly via tumor cell cytotoxicity induced by TNF-a and ROS or indirectly through the synthesis of interleukin-9 and heparin and the initiation of dendritic cell maturation." (PMID 37256127, 2023). "These M1 macrophages are characterized by their ability to present antigens, kill tumor cells, and produce pro-inflammatory cytokines like IL-12 and TNF-α, thereby enhancing antitumor immunity." (PMID 37895855, 2023). "Tumor necrosis factor-alpha (TNF-α), an inflammatory cytokine promotes tumor growth and higher serum levels of TNF-α have been reported to be associated with poor prognosis in cancer patients." (PMID 36879122, 2023). "Pretreatment with a neutralizing anti-TNF-α antibody or Si-RNA of TNF-α resulted in rescue from tumor cell death led by the birinapant and chemotherapeutic drugs." (PMID 36831656, 2023). "In line with the previous study results, tumor growth was suppressed by anti-TNFα mAb in the orthotopic transplantation model used in this study." (PMID 36996146, 2023). "Results showed that these nanoparticles had increased IL‐12 and TNF‐α (antitumor chemicals) levels with a simultaneous decrease in IL‐6 and IL‐10 (pre‐tumor cytokines)." (PMID 38455223, 2023). "EGCG’s downregulation of NF-κB would prevent the production of these cytokines as exemplified by TNFα in tumor cells, leading to disruption of tumor and stromal interactions." (PMID 36677584, 2023). "One proposed treatment involves targeted chemotherapy that delivers a tumor-killing agent, TNFα, to malignant tumors." (PMID 37895881, 2023). "TNF-α kills and restrains the growth of tumor cells, also promotes cell proliferation and differentiation." (PMID 37060101, 2023). "TNFα generation was also negatively impacted by tumor exposure, with most of the decrease being driven by the TIGIT/PVR axis." (PMID 37345049, 2023). "In MDA-MB-231 cells, the expression of three tumor suppressor genes was significantly upregulated by fucoxanthin compared to TNF-α alone." (PMID 38202644, 2023). "IFN-γ can also interact with other receptors on tumor cells via Fas ligand, tumor necrosis factor (TNF), TNF-related apoptosis-inducing ligand (TRAIL), and lymphotoxin alpha, which in turn enables apoptosis." (PMID 38139779, 2023). "TNF-α as a major pro-inflammatory cytokine is usually involved in tumor proliferation, and metastasis." (PMID 37338718, 2023). "While the M1 macrophages produce TNF-α, IL-6, and chemokines that maintain the inflammatory environment in the tumor, the M2 macrophages promote angiogenesis, growth, and metastasis of tumor tissue." (PMID 36937317, 2023).
tumor (continued). "Single-cell suspensions of RCC tumours at different stages of the disease were stimulated in vitro to assess the ability of the T-cells to produce IFNΥ and TNFα and compared to T-cells from the blood of the patients or healthy controls." (PMID 37940720, 2023). "The analyses were performed on the basis of the time period of in-tumour induction incidence, haematological parameters, histopathology and augmentation of TNF-α secretion and the NF-κB (p65 subunit) signalling pathway." (PMID 38067358, 2023). "As TLR activation can stimulate the production of IFNs, interleukins and TNF by myeloid and lymphoid cells, the evidence points towards reduced inflammatory and immune cell signalling within tumours from UE2316-treated mice." (PMID 36940215, 2023). "Radiation resistance occurs when TNF-α directly mediates the differentiation of monocytes into angiogenic cells, which support tumor vessel growth, and promotes VEGF production by macrophages by binding with TNFR on macrophages in an autocrine manner." (PMID 37208386, 2023). "These tumors were characterized by NFκB, Akt, Stat-3 activation, increased proliferation, and upregulation of important innate immune players such as GM-CSF, M-CSF, MCP-1 and TNFα from tumor derived cells." (PMID 37543673, 2023). "Upregulation of CD39 was accompanied by the expression of inhibitory receptors and reduced IL-2 and TNF secretion, and tumor growth, indicating CTLs’ exhaustion." (PMID 37835465, 2023). "QYSL promoted the polarization of M1 macrophages and inhibited tumor growth by promoting the expression of TNF-α, IL-1, and IL-12." (PMID 37355637, 2023). "In this respect, two independent groundbreaking studies give strong evidence that tumor cell-expressed TRAF2 antagonizes the efficacy of checkpoint inhibitor therapies by protection against cell death induction by CD8+-derived TNF." (PMID 37545514, 2023). "TNFα is reported to synergize with IFNγ to induce Jak1/Stat1-dependent tumor cell death and recruit cytolytic T cells to the tumor microenvironment." (PMID 36968224, 2023). "We also detected positive correlation between Iso2 levels and TNF-α levels in human HCC tumor tissues and determined increased numbers of CD3+ T cells in Iso2pos tissues, regardless of the expression of Iso1." (PMID 37047287, 2023). "Hereof, increased levels of IL1β, IL8, MCP1 and TNFα have been related to tumour progression and metastasis in HNSCC." (PMID 37460712, 2023). "First, we measured the ability of the REP TILs to produce the cytokines IFNγ and TNFα when cocultured with the tumor cells." (PMID 37484198, 2023). "The combination effect not only activated CD4+ and CD8+ T cells and NK cells and promoted the secretion of cytokines (TNF-α and IL-12) but also increased the tumour inhibition rate to 84.2%." (PMID 37514054, 2023). "Estrogen receptor β (Erβ) reduce the occurrence and development of tumor by reducing macrophage infiltration and reducing the production of TNF-α." (PMID 37006260, 2023). "TNFRSF1B encodes the receptor for tumor necrosis factor-α (TNFR2), which plays a crucial role in promoting tumor growth, invasion, and metastasis." (PMID 37108754, 2023). "In striking contrast to BMDMs stimulated with LPS and IFN-γ, CDDO-Me increased TNFα (p < 0.0001) and IL-6 (p < 0.001) mRNA ~4-fold in WT tumor-educated BMDMs." (PMID 36670978, 2023). "Upregulation of TNF-α is often observed, ultimately leading to hemorrhage and eventually the inhibition of tumor angiogenesis." (PMID 37514190, 2023). "AMs isolated from lung cancer patients when stimulated with IFN-γ or GM-CSF, secrete TNF-α, IL-6, and IL-1β, that can enhance tumor killing." (PMID 37822933, 2023). "Previous studies have indicated that excessive secretion of IFN-γ, TNF-α, interleukin and other pro-inflammatory cytokines by T cells in the tumor microenvironment induce the expression of PD-L1 in tumor cells." (PMID 36717584, 2023).
tumor (continued). "COX-2 is nearly not present in normal tissues but can be induced by growth factors, cytokines, TNF-α, and vascular activator peptides to participate in tumor growth, metastasis, invasion, and angiogenesis." (PMID 37547718, 2023). "Given TNF-α’s role in tumor surveillance, it is natural to expect TNF-α blockade to negatively affect cancer progression." (PMID 37958355, 2023). "TNF-α induces the expression of vascular cell adhesion molecule-1 (VCAM-1), which has pro-angiogenic potential and is tightly associated with tumor angiogenesis and tumor cell invasion." (PMID 37686525, 2023). "The further hallmarks of T cell activation upon tumor lysis, levels of cytokines released in culture supernatants by T cells were measured, including IL-2, TNF-α and IFN-γ." (PMID 37488603, 2023). "Analysis of tetramer+ TILs from triple-treated mice in both tumor models showed that the percentage of polyfunctional (IFNγ+TNF+) cells decreased from the TCF1+TIM3-PD1+ to the CD101-TCF1-TIM3+PD1+ to the CD101+TCF1-TIM3+PD1+ subset." (PMID 37045833, 2023). "It is worth noting that FOXA1 target genes were mainly enriched in pathways related to apoptosis, mitosis, mTOR, TNF-α, indicating its possible involvement in tumor malignant proliferation and supporting our fold enrichment of CERES scores above." (PMID 37876590, 2023). "ILC1s are defined by the master transcription factor T-bet and are activated by the presence of IL-12, IL-15, and IL-18 to mount an anti-viral and anti-tumor response by producing effector cytokines IFNγ and TNF-α." (PMID 38567059, 2023). "In fact, TNF-α-induced tumor-specific Tc9 cells displayed enhanced antitumor capabilities compared to the those of control Tc9 cells." (PMID 37907738, 2023). "It is suggested that tonic Chinese herbal medicine polysaccharides can increase the level of TNF-α in tumor-bearing mice, thus killing tumor cells and improving immune function." (PMID 37959774, 2023). "In the context of immunotherapy, CD8+ T cells play a pivotal role, secreting cytokines such as IFN-γ, TNF-α, and IL-2 to exert cytotoxic effects on tumor cells." (PMID 38299141, 2023). "The first clinical trial (identifier: NCT00356980), which begun in 2006, involved Aurimune CYT-6091 (Cytimmune), the first tumor-targeted nanostructure consisting of 27 nm pegylated AuNPs conjugated with a tumor necrosis factor alpha (TNF)." (PMID 36839822, 2023). "When stimulated by pro-inflammatory cytokines such as IL-1α, IL-1β, and tumor necrosis factor α, CAFs tend to shift towards a senescent state, inhibiting tumor cell apoptosis and promoting tumor cell dissemination." (PMID 38013358, 2023). "In our previous work, we have identified a differential reliance on TRAF2 and BIRC2 to establish resistance to TNF in different tumor cell lines." (PMID 37398651, 2023). "M1 macrophages exhibit an anti-tumor role by releasing pro-inflammatory cytokines, including interleukin-12 (IL-12) and tumor necrosis factor-alpha (TNF-α)." (PMID 38022589, 2023). "The pro-inflammatory cytokines IL-1β, IL-6, and TNF-α are involved in tumor cell proliferation, angiogenesis, and metastasis and seem to strengthen each other’s mode of action, these being stimulated by the same mediators." (PMID 38137862, 2023). "While often critical for the immune response to pathogens, pro-inflammatory cytokines (TNFα, IL-1β, and IL-6) play mixed roles in tumor pathogenesis." (PMID 37461742, 2023). "CD4+ T cells can secrete cytokines, such as interferon-gamma (IFN-γ) and tumour necrosis factor-alpha (TNF-α), which directly kills tumour cells." (PMID 38130720, 2023). "When LCMV-primed T cells and tumor cells were co-incubated, 5-NL increased the expression of TNF alpha (TNFα), GZMB and IL-2 in CD8+ T cells incubated with B16.GP33 but not B16 cells." (PMID 37582744, 2023). "Knockdown of E3 ubiquitin ligase Cbl-b increased CAR T-cell effects and blocked CD8+ T-cell exhaustion, upregulated the expression of IFN-γ and TNFα, and accelerated tumor cell killing." (PMID 36733484, 2023).
tumor (continued). "In mouse models, blockade of TIGIT restored NK cell cytotoxicity, increased IFNγ and TNFα expression, and promoted tumor-specific T cell immunity." (PMID 37345049, 2023). "Using gene ontology and pathway analysis, we identified pathways with known function in regulating tumor resistance such as IFN-γ, TNF-α, NF-κβ, autophagy but also novel pathways related to tumor intrinsic immune evasion." (PMID 37732732, 2023). "Conversely, co-cultures of CD26− NFs and tumor cells secreted more TNFα and CD54 compared to co-cultures of CD26+ NFs and tumor cells." (PMID 36635273, 2023). "Consistently this cytokine is frequently present in the tumour microenvironment, and tumour cells usually acquire resistance to TNFα-induced cell death." (PMID 36900285, 2023). "In the 4T1-related breast carcinoma model, mixed leucocyte cultures of tumor-bearing mice secrete markedly higher levels of IL-6 and TNF-α, and lower levels of IFN-γ." (PMID 37371563, 2023). "Effector T cells also produce cytokines such as interferon-gamma (IFN-γ) and tumor-necrosis factor alpha (TNF-α) leading to tumor cell apoptosis." (PMID 38550850, 2023). "Mechanistically, IFNγ induces the expression of cytokines IL-1β, IL-6, IL-12, IL-18, IL-23, TNFα, and proinflammatory factors such as ROS and NO by M1 macrophages, thereby contributing to M1 macrophage-mediated anti-tumour immunity." (PMID 37455828, 2023). "TNF-α is a proinflammatory cytokine that functions in cytokine expression, tumor necrosis, and neutrophil activation." (PMID 38024366, 2023). "In consistent with results in tumour tissues, the expression of TNF‐α was comparable between KO/TAMs and WT/TAMs." (PMID 36419386, 2023). "TNF-α-induced ROS generation are known to upregulate skin aging-related molecular pathways such as MAPKs and NF-κB, while ROS trigger the activation of MAPKs phosphorylation, which in turn upregulates the transcriptional pathways NF-κB and AP-1." (PMID 37507970, 2023). "Among these, microRNA-21 (miR-21) is an oncogenic miRNA, the overexpression of which can downregulate key tumor inhibitory proteins, such as programmed cell death protein, TNFα (tumor necrosis factor-α), ERK (extracellular signal-regulated kinase), and VEGF." (PMID 37759618, 2023). "Because of the high metabolic activity of adipose tissue, pro-inflammatory factors such as interleukin (IL)-6 and tumor necrosis factor (TNF)-alpha secreted by this tissue can initiate tumor formation." (PMID 36860687, 2023). "M1 TAMs function as antigen-presenting cells (APCs), expressing Interleukin 12 (IL12) and tumor necrosis factor (TNF) to combat tumor cells." (PMID 37896181, 2023). "CD68+ M1 macrophages, known for its tumor-inhibiting ability, are the major TNF-α-producing immune cells in the tumor microenvironment." (PMID 38037106, 2023). "M2 macrophages release epidermal growth factor, chemokines (such as CCL24and CCL22), and cytokines (such as TNF-α and IL-6) that directly promote tumor growth and metastasis and promote tumor progression." (PMID 37153586, 2023). "For instance, M1-like particles are preferable in the development of anti-tumor drug delivery systems, since the abundance of TNF-α and other pro-inflammatory cytokines results in a high tumor accumulation capacity." (PMID 37999184, 2023). "Accordingly, TGF-β1, IL-10 and CCL2 protein levels were significantly increased, and TNFα, IL-6, IL-1β and IL-12p40 protein levels were significantly decreased in tumor tissues in mice with MO-Mettl3 macrophages compared with mice with MO–nc macrophages." (PMID 37402945, 2023). "Among them, MMP9 was associated with macrophage M0 in 12 tumor types, PTGS2 was associated with six immune cell types among six tumor types, and TNF with seven immune cell types in five tumor types." (PMID 37033970, 2023).